NRAS (NRAS proto-oncogene, GTPase)
Diseases named in the same sentence as NRAS in open-access papers (continued):
Sharing a sentence is not in itself a finding about the gene and the disease.
melanoma (continued). "Regarding melanoma therapy resistance, beyond BRAF and NRAS, other pivotal genes come to the forefront." (PMID 39582535, 2024). "The fact that BRAF and NRAS genes were mutated in the analyzed advanced-stage NeM patients, suggests that the biology of NeM corresponds to that of classical melanoma, further supporting the interpretation of this melanoma as a diagnostic challenge, rather than a distinct biological entity." (PMID 39796694, 2024). "Analysis of the BRAF, NRAS, and NF1 genes in patient samples will allow for the classification of melanoma into four proposed molecular subtypes." (PMID 39340537, 2024). "In view of the fact that the OFA includes some relevant genes in melanoma pathways apart from BRAF, such as NRAS, KIT, or MAP2K1, we embraced this panel to prospectively study a series of advanced melanoma patients." (PMID 39000050, 2024). "For melanoma, it has been widely used to study the effects of BRAF or NRAS (key initiating events in melanoma) and has uncovered important developmental and microenvironmental influences on these tumors." (PMID 36472402, 2023). "NRAS and BRAF are altered in melanoma (17% and 55%, respectively), thyroid carcinoma (19% and 55%, respectively), and lung cancer (1% and 5%, respectively)." (PMID 37370689, 2023). "In a mouse model with NRAS-driven melanomagenesis, Tet2 cooperated with oncogenic NRASQ61K to promote melanoma initiation while suppressing specific gains in 5hmC." (PMID 37834158, 2023). "One paper reported DUSP4 deficiency leading to impaired cell proliferation and cell death in NRAS and BRAF mutant melanoma cells." (PMID 37946160, 2023). "The genetic makeup of the triple-wild-type melanoma (BRAF, NRAS and NF1) has been known for some time, but those studies grouped together rare histopathological versions with common ones, as well as mucosal and even uveal ones." (PMID 36980598, 2023). "Deregulation of two major signalling pathways, the RAS-RAF-MEK-ERK and PI3K-AKT-PTEN, are key drivers of melanoma development and progression, with ~50% and ~25% of patients expressing constitutively active mutants of MAP-kinases BRAF and NRAS, respectively." (PMID 37495601, 2023). "According to the four main melanoma genetic subtypes established by The Cancer Genome Atlas (TCGA), we found 52.8% (19/36) BRAF-mutant, 30.6% (11/36) NRAS-mutant, 8.3% NF1-mutant, and 13.9% (5/36) triple wild-type melanomas." (PMID 36901733, 2023). "Molecular testing for common melanoma driver genes, including BRAF, NRAS, KRAS, HRAS, NF1, and KIT, was available for this study." (PMID 37686691, 2023). "(ρ = 0.524) In a next step we analyzed the TCGA (melanoma) and GTEx (healthy skin) databases for potential alterations of gene expression of MALAT1 in relation to NRAS, BRAF, MEK1, MEK2, ERK1 and ERK2 gene expression." (PMID 37235843, 2023). "Similarly, as suggested previously, an alternative hypothesis could be that the biology of melanoma is similar to that of other cancers where biology drives mutual exclusivity, for example activation of the MAPK pathway via either BRAF or NRAS mutation, but chance explains most co‐occurrences." (PMID 36219477, 2023). "Currently, four genomic subgroups of melanoma have been identified through studies of The Cancer Genome Atlas (TCGA) network: BRAF (B-rapidly accelerated fibrosarcoma), NRAS, NF1, and triple wild type." (PMID 37446286, 2023).
melanoma (continued). "These cell lines, which included a range of cancer types (lung, melanoma, or breast) and oncogenic drivers (KRASG12S, BRAFV600E, and PTEN, respectively), showed accumulation of NRAS and KRAS under MEKi treatments." (PMID 37370689, 2023). "Collectively, these data suggest that combined immune checkpoint blockade and HDAC inhibition can stimulate T cell immunity against human UM in vitro and BRAF, NRAS, and NF1 wildtype melanoma in vivo." (PMID 34753889, 2022). "In NRAS mutant patients of the validation cohort, NOTCH4 wildtype melanoma had longer OS (mOS: 31.3 months vs. 22.6 months, HR = 1.23, 95% CI: 0.48–3.18, P = 0.68) than NOTCH4-Mut patients." (PMID 35967450, 2022). "Ulixertinib (BVD-523) has shown early evidence of clinical activity in a phase I trial, that included both patients with NRAS-mutant melanoma and BRAF-mutant melanoma which progressed on or were refractory to BRAF and/or MEK inhibitors." (PMID 35053435, 2022). "In NRAS mutant patients of the discovery cohort, NOTCH4-Mut melanoma had longer OS (mOS: 34.93 months vs. 6.43 months, HR = 0.37, 95% CI: 0.09–1.61, P = 0.17) than wildtype melanoma, but there was no statistical difference." (PMID 35967450, 2022). "On these bases, in melanoma, the inhibition of RAS-prenylation has been suggested as a possible therapy in NRAS-mutant tumors." (PMID 36400750, 2022). "We used two-color PALM to study the dynamics of NRas and BRAF organization at the PM of live (108T) melanoma cells, in single molecule detail." (PMID 36304112, 2022). "In patient‐derived short‐term melanoma cultures, higher DDR1 and DDR2 protein levels were detected in BRAF mutant MM099 and MM029 and NRAS mutant MM165 cells with the MITFlow, SOX10low, and AXLhigh de‐differentiated phenotype signature." (PMID 34957688, 2022). "However, no MEK inhibitor was approved for melanoma patients with NRAS mutation worldwide." (PMID 36386136, 2022). "Based on the findings of these studies, it can be speculated that NRAS may be an important factor in melanoma that affects the efficacy of immunotherapy and that studies on biomarkers should use NRAS status as a classification factor for the melanoma population." (PMID 35967450, 2022). "The CE-IVD labels for Idylla molecular assay are assigned only to specific tumor types for each assay-NSCLC for EGFR; CRC for KRAS, NRAS-BRAF and MSI, and melanoma for BRAF." (PMID 36293374, 2022). "To examine the effect of KDs on melanoma growth, we established BRAF mutant (A375 and WM47), BRAF/NRAS/NF1 wild-type (WM3311), and NRAS mutant (WM3000) xenografts in CD-1 nude mice." (PMID 35851093, 2022). "Altogether, these data suggest the existence of a feedback loop upon metabolic stress in NRASQ61mutant melanomas between the RAS pathway and the glycolytic route, connecting BRAF, PFKFB2, PFK1, SOS1/2 and NRAS." (PMID 36402789, 2022). "To date, the targeted therapy for NRAS-mutant melanoma is based on MEK inhibitors, unfortunately with efficacy lower than that designed for BRAF-mutant melanoma." (PMID 36400750, 2022). "It has to be emphasized that the KIT receptor signaling pathway, containing NRAS and BRAF, is the dominating pathway in melanocytes (and evidently in melanoma), and it is responsible for activating the melanocyte-specific transcription factor MITF." (PMID 35628196, 2022). "Despite the association of NRAS-mutant tumors with CSD skin, it is reported that UV signature lesions (C>T and CC>TT) are prevalent in a similar proportion of NRAS- and BRAF-mutant melanomas." (PMID 34210801, 2021).
melanoma (continued). "As a result, melanomas have been classified into four distinct genetic subsets based on the molecular signature (BRAF mutant, NRAS mutant, NF1 mutant, and triple negative)." (PMID 34831002, 2021). "Melanomas with NRAS-mutant cells and BRAF-mutant cells have greater resistance to BRAF inhibitors, likely due to selection of NRAS mutant populations." (PMID 35008286, 2021). "Of these, one had a BRAF mutant melanoma (ETH-E), two had NRAS mutant melanomas (SK-G & ETH-J), and three were BRAF/NRAS/NF1 wild-type (MI-F, SK-H, ETH-F)." (PMID 33664264, 2021). "Moreover, according to AACR GENIE, in human the NRAS p.Gly12Asp was detected in acute myeloid leukaemia, colon adenocarcinoma, colorectal adenocarcinoma, rectal adenocarcinoma, acute myeloid leukaemia with myelodysplasia-related changes and in melanoma patients." (PMID 34643354, 2021). "NRAS, KIT, EGFR, MET, RAB27A, and other pro-progression proteins have all been found within exosomes released by melanomas." (PMID 35008286, 2021). "Identifying which human melanoma subtypes (e.g., BRAF, NRAS, c-KIT, etc) in which an interface cell state is found awaits larger datasets of freshly isolated tumors subjected to scRNA-seq and/or SRT." (PMID 34725363, 2021). "Nelfinavir improves the approach of targeted melanoma therapy by sensitizing BRAF and NRAS mutant melanomas to MAPK pathway inhibitors." (PMID 33918792, 2021). "These genomic subtypes include BRAF-mutant melanoma (50%), NRAS, KRAS and HRAS-mutant melanoma (25%), NF1-mutant melanomas (15%) and triple wild-type melanomas (10%)." (PMID 34572747, 2021). "Using genome-scale analyses, melanoma has been classified into four distinct groups based on their NRAS, BRAF, and NF1 status: NRAS-mutant, BRAF-mutant, NF1-mutant, and triple-negative (NRAS/BRAF/NF1 mutant) melanoma." (PMID 33766731, 2021). "Ribociclib was evaluated with Binimetinib (NRAS/MEK inhibitor) or Encorafenib (BRAF inhibitor) in two different Phase I/II clinical trials in advanced NRAS and BRAF mutant melanoma." (PMID 34071228, 2021). "Genetic alterations in BRAF and NRAS, as well as a handful of tumor suppressors such as NF1, CDKN2A, ARID2 and PTEN, have been shown to contribute to melanoma pathogenesis." (PMID 33958721, 2021). "Class I BRAF mutant melanomas also acquire resistance to RAFi via increases in RTK and NRAS expression, which increasing the proportion of active RAF." (PMID 33367512, 2021). "Malignant melanoma has been classified in four subgroups according to its main genetic drivers by The Cancer Genome Atlas: mutant BRAF, mutant NRAS, mutant NF1, or triple wild-type tumors." (PMID 34362135, 2021). "We have shown that the RICTOR locus is frequently amplified in melanomas and that the overexpression of RICTOR in melanocytes transformed by the NRAS oncogene stimulates their clonogenicity." (PMID 34680615, 2021). "In the Asian population predominantly with acral and mucosal melanoma, the ORR of NRAS mutant patients was only 6.1% (1/16) to anti-PD-1 monotherapy." (PMID 34290710, 2021). "We detected frequent and common aberrations shared by the primary tumors and melanoma metastases on chromosome 7, where BRAF localizes, while CNGs on chromosome 1 bearing NRAS was a metastases-only feature." (PMID 34885093, 2021). "In general, mutant NF1 melanoma contain WT BRAF and WT NRAS, and rather carry comutations in the so-called RASopathy genes (PTPN11 or RASA2)." (PMID 34362135, 2021). "NRAS Q61R is present in 0.73% of AACR GENIE cases, and has been identified in cutaneous melanoma, melanoma, papillary thyroid cancer, poorly differentiated thyroid gland cancer, and colon adenocarcinoma." (PMID 34525976, 2021).
melanoma (continued). "We used the syngeneic NRASQ61K 1007 model, which mimics the human NRAS-mutant model, to address the efficiency of [131I]ICF01012-TRT in this pigmented melanoma." (PMID 33804655, 2021). "A panel of melanoma cell lines, harboring wild type or mutant BRAF and NRAS, showed sensitivity to the six EOs, even if at a different extend, thus indicating that the effect of EOs was not related to BRAF or NRAS status." (PMID 34059622, 2021). "NRAS and BRAF both play a part in the MAPK pathway, which are thought to contribute to melanoma development." (PMID 34350118, 2021). "Due to the binding of miR-145-5p and activation of NRAS/MAPK signaling by RP11-705C15.3, we next investigated the potential biological roles of RP11-705C15.3 in melanoma." (PMID 33311650, 2021). "Part of the investigational effort focuses on targeting downstream effectors or parallel pathways that are essential for NRAS and NF1 mutant melanomas, and another investigation is focused on the combined targeted therapy approach." (PMID 34831002, 2021). "The same applies for melanoma cells with BRAF and NRAS wild-type proteins as we demonstrated in a previous study." (PMID 32098410, 2020). "Upon further characterization, it was demonstrated that SBI-756 impaired eIF4F complex formation in melanoma cells and inhibited the growth of BRAF, NRAS, and NF1-mutant melanoma cell lines." (PMID 32517051, 2020). "The initial skin lesion was a BRAF-mutant melanoma with Spitzoid features and termed as AST, while the giant lung metastasis was NRAS-mutant melanoma." (PMID 33100226, 2020). "We have found a large diversity of transcript levels between three representative melanoma cell lines, and this was also observed when transcript levels of three selected genes were assessed in six cell lines of either the BRAF or NRAS subtype." (PMID 32466509, 2020). "The systematic evaluation of over 500 melanoma genomes in the last decade has identified a series of frequently and significantly altered oncogenes and tumor suppressor genes, including BRAF, NRAS, RAC1, NF1, CDKN2A, PTEN, and ARID2." (PMID 33076392, 2020). "Ganetespib exerted similar activity in melanoma cells of different genetic subtypes including those harboring both BRAF and NRAS as wild-types." (PMID 31659567, 2020). "All 37 were wild type for BRAF, NRAS, and NF1 genomic alterations (“triple wild-type”), representing 2.0% of triple wild-type melanomas overall (37/1882)." (PMID 32483240, 2020). "We selected four melanoma cell lines for analysis: SKMEL5 and SKMEL28 (BRAF mutant), and SKMEL2 and IPC298 (NRAS mutant)." (PMID 32488085, 2020). "FUT8-AS1 exerts its tumor suppressive roles via binding NF90, relieving the repressing roles of NF90 on miR-145-5p biogenesis, upregulating miR-145-5p, repressing NRAS, and lastly repressing MAPK signaling in melanoma." (PMID 34094894, 2020). "Most relevant molecular drivers that participate to melanoma metabolic plasticity include AKT, BRAF, p14ARF, MYC, NRAS, phosphatidylinositol-4,5-bisphosphate 3 kinase catalytic subunit α (PIK3CA) and phosphatase and tensin homolog (PTEN)." (PMID 32528879, 2020). "For this purpose, melanoma cell lines with mutant BRAF, NRAS, or cKIT and with acquired resistances to BRAF, MEK, or cKIT inhibitors, respectively, were investigated using both 1H-NMR-based metabonomic and protein microarrays." (PMID 32455924, 2020). "In line with expectation, our results showed that FUT8-AS1 represses the expression of NRAS and further represses MAPK signaling in melanoma." (PMID 34094894, 2020). "This was expected in the context of the molecular landscape of melanomas that can be divided into four distinct subclasses, including BRAF subtype and NRAS subtype." (PMID 32784823, 2020).
melanoma (continued). "RAS proteins (KRAS, NRAS and HRAS) are frequently activated in different cancer types (e.g., non-small cell lung cancer, colorectal cancer, melanoma and bladder cancer)." (PMID 33187149, 2020). "Concentrations down to 30 μmol L−1 magnolol‐induced apoptosis and cell death in NRAS‐ and BRAF‐mutant melanoma cells, whereas BRAF/NRAS wild‐type melanoma cells were only susceptible at higher concentrations (80 μmol L−1)." (PMID 30793515, 2019). "Alterations of the oncogenes BRAF and NRAS, which act through the MAP-kinase pathway, are the most frequent early events that drive melanocyte proliferation in both nevi and melanoma." (PMID 31861163, 2019). "Pharmacological co-targeting of NFATc2 and EZH2 exerted significant anti-tumor effects in distinct melanoma subsets, including BRAF-mutant but BRAF-inhibitor-resistant cell lines, as well as NRAS mutant and BRAF/NRAS wild-type tumors." (PMID 30710146, 2019). "Although the main driver genes (BRAF, NRAS, C-KIT, NF, GNAQ) have been discovered, these markers cannot act as individual indicators for every melanoma case." (PMID 30900145, 2019). "Binimetinib is a highly selective MAPK kinase (MEK) 1/2 inhibitor with clinical antitumor activity in NRAS- and BRAFV600-mutant melanoma." (PMID 30956763, 2019). "Contrary to NRAS mutant cases, in BRAF-mutant melanomas MAFs were found to be significantly increased in visceral metastases compared to the primary due to the significantly higher levels in lung-, adrenal gland-, intestinal- and kidney metastases." (PMID 31391014, 2019). "Indeed, up to 80% of all melanomas harbor activating NRAS or BRAF mutations, with BRAFV600E representing more than 90% of BRAF mutations, resulting in constitutive activation of the signaling pathway, promoting melanoma proliferation and resistance to apoptosis." (PMID 31780644, 2019). "We focused our work on NRAS and BRAF because there is sufficient genomic data available in mucosal melanoma." (PMID 31398831, 2019). "Researchers with The Cancer Genome Atlas (TCGA) Network identified four genomic subgroups of melanoma: BRAF, NRAS, NF1, and triple wild-type." (PMID 30675668, 2019). "Mutations of key proteins in the RAS/RAF/MEK/ERK and PI3K/Akt/mTOR signaling cascades were described in malignant melanoma including BRAF (35–60%), NRAS (15–30%), and PTEN (8–15%)." (PMID 31623406, 2019). "NRAS and BRAF both play a part in the mitogen-activated protein kinase (MAPK) pathway, which significantly contributes to melanoma development." (PMID 31398831, 2019). "Different BRAF, NRAS, Nf1 and KRAS mutant-driven syngeneic mouse melanoma models have been created and characterized." (PMID 31416487, 2019). "We employed SynGeNet to generate drug combination predictions for each of the four major genomic subtypes of melanoma (BRAF, NRAS, NF1, and triple wild type) using publicly available gene expression and mutation data." (PMID 30820351, 2019). "Magnolol, honokiol, and derivates were first assessed for their efficacy in NRAS‐mutant WM1366 and BRAF‐mutant WM164 melanoma cells by crystal violet assay." (PMID 30793515, 2019). "MEKis or ERKi, also combined well with AZD5991 in NRAS-mutant MEL-JUSO, SK-MEL-2, SK-MEL-30 and WM852 melanoma cells." (PMID 31727888, 2019). "To understand CDK11 function in melanoma, we evaluated protein and RNA levels of CDK11, Cyclin L1 and Cyclin L2 in benign melanocytes and BRAF- as well as NRAS-mutant melanoma cell lines." (PMID 30987032, 2019). "Melanomas which are wild type for BRAF, NRAS, and NF1 show amplifications of KIT, platelet-derived growth factor receptor α (PDGFRA), and vascular endothelial growth factor receptor 2 (VEGFR2) in 10–20% of cases." (PMID 30987166, 2019). "Crucially, pharmacological co-targeting of NFATc2 and EZH2 exerted significant anti-tumor activity not only against BRAF-mutant melanomas with intrinsic resistance to BRAF inhibitors, but even against NRAS-mutant and BRAF/NRAS wild type melanoma cells." (PMID 30710146, 2019).